EWSR1 (EWS RNA binding protein 1)
Diseases named in the same sentence as EWSR1 in open-access papers (continued):
Sharing a sentence is not in itself a finding about the gene and the disease.
neuroepithelial tumor (5 papers, 2022 to 2025). "The region of INI1 inactivation could indicate either ATRT transformation within an ependymal-like neoplasm, or an acquired accompanying mutation associated with tumor progression in an EWSR1-PLAGL1 neuroepithelial tumor." (PMID 39228008, 2024). "A histologic feature observed on initial resection in a subset (4/6) of supratentorial neuroepithelial tumors with EWSR1-PLAGL1 rearrangement was the presence of concurrent ependymal and ganglionic differentiation." (PMID 39228008, 2024). "Case 2 did not demonstrate a match on methylation profiling, and in the context of known abnormal molecular drivers provided an integrated diagnosis of a neuroepithelial tumor with EWSR1-ATF fusion." (PMID 35994156, 2022). "As such, EWSR1-PLAGL1 neuroepithelial tumors are a tumor type in which acquired inactivation of SMARCB1 and development of AT/RT features may occur and lead to clinical progression." (PMID 39228008, 2024). "Neuroepithelial tumors (NET) with PATZ1 fusions (NET-PATZ1) have been isolated by a distinct DNA methylation profile and are characterized by recurrent fusions of PATZ1 in association with EWSR1 or MN1 genes." (PMID 35115049, 2022). "When present, the combination of ependymal-like and ganglionic features within a supratentorial neuroepithelial tumor may raise consideration for an EWSR1-PLAGL1 fusion, and prompt initiation of appropriate molecular testing such as RNA sequencing and methylation profiling." (PMID 39228008, 2024). "A novel DNA methylation class of tumor within the central nervous system, the "neuroepithelial tumor (NET), PATZ1 fusion-positive” has recently been identified in the literature, characterized by EWSR1- and MN1-PATZ1 fusions." (PMID 35115049, 2022). "It is likely that prior to clinical availability of RNA sequencing and methylation profiling, many cases with undetected EWSR1-PLAGL1 fusion were histologically diagnosed as ependymoma, while some cases may have been considered a type of anaplastic ganglioglioma or high-grade neuroepithelial tumor." (PMID 39228008, 2024).
pancreatic cancer (5 papers, 2013 to 2022). "GDSC analysis showed that mTOR inhibitors are very sensitive to pancreatic cancer cells with mutations in EWSR1.FLI1 and RNF43." (PMID 34461940, 2021). "In addition, we used the GDSC database analysis to prove that the mTOR inhibitor (GSK2126458) is very sensitive to pancreatic cancer cell lines, especially for EWSR1.FLI2 and RNF43 mutant." (PMID 34461940, 2021).
chronic myeloid leukemia (4 papers, 2011 to 2019). "Gene fusions confirming diagnosis were found in five patients: BCR-ABL1 (chronic myeloid leukemia), ASPSCR1-TFE3 (alveolar soft part sarcoma), EWSR1-FLI1 in two patients (Ewing sarcoma), and EWSR1-WTI (desmoplastic small round cell tumor)." (PMID 28007021, 2016).
glioblastoma (4 papers, 2015 to 2024). The most malignant astrocytic tumor (WHO grade IV). "Compared with classic glioblastomas, EWSR1::PATZ1 tumors generally exhibit better survival, although data remain limited owing to their rarity." (PMID 39583630, 2024). "Similarly, the RBP EWSR1 was identified to aggregate in the cytoplasm in temozolomide (a chemotherapeutic agent)-resistant glioblastoma cells and patient samples." (PMID 35954405, 2022). "The histopathological appearance of tumors harboring the EWSR1::PATZ1 fusion is diverse, encompassing entities such as ependymomas, high‐ and low‐grade astrocytomas, glioblastomas, and gangliogliomas." (PMID 39583630, 2024). "One article technically met the inclusion criteria but was excluded because it described a tumor that developed the EWSR1::PATZ1 fusion many years later, at the recurrence as a glioblastoma (GBM), making it unlikely that the fusion was the genetic driver mutation." (PMID 39583630, 2024).
astroblastoma (3 papers, 2023 to 2025). "EWSR1::BEND2 fusions are recurrent in a specific subtype of astroblastoma that is closely related to ‘astroblastoma, MN1-altered′, an entity that harbors MN1 GF with BEND2 as the typical partner, but they are slightly different in their methylation profile." (PMID 38339014, 2024). "Additionally, the detection of MN1 or EWSR1 gene fusion through FISH or next-generation sequencing can provide valuable insights into the molecular mechanisms and aid in the differential diagnosis of astroblastoma." (PMID 39963393, 2025). "The EWSR1(Exon1-7)-NUDT10(Intergenic) fusion is a newly discovered fusion, indicating a novel chromosomal fusion pattern not previously observed in astroblastoma tumours." (PMID 39963393, 2025).
colorectal cancer (3 papers, 2021 to 2025). A primary or metastatic malignant neoplasm that affects the colon or rectum. "EWSR1 fusions have rarely been described in adenocarcinomas such as colorectal cancer." (PMID 36013219, 2022). "The DLD-1 colorectal cancer cell line was chosen because it does not express EWSR1/FLI1 endogenously, and because it has a near-diploid karyotype, it has been used as a model to evaluate proteins of interest for their ability to induce aneuploidy." (PMID 33293370, 2021).
cutaneous melanoma (3 papers, 2003 to 2014). A primary melanoma arising from atypical melanocytes in the skin. "As EWSR1 gene fusions had not previously been described in cutaneous melanoma, we prioritized CHL-1 and SH4 for further evaluation." (PMID 23637631, 2013).
dermatofibrosarcoma protuberans (3 papers, 2024 to 2025). Dermatofibrosarcoma protuberans (DFSP) is a rare infiltrating soft tissue sarcoma, generally of low grade malignancy, arising from the dermis of the skin and characteristically associated with a specific chromosomal translocation t(17;22). "The frequency of fusions was also high in desmoplastic small round cell tumors (77.8%; 7 of 9 samples) and in dermatofibrosarcoma protuberans (100%; 4 of 4 samples), driven by EWSR1 or COL1A1 fusions, respectively." (PMID 40711866, 2025). "The partial amplification pattern might be compatible with fusion of the involved genes, similar to cases described in dermatofibrosarcoma protuberans, with COL1A1::PDGFB or in case of EWSR1::NFATC2 fusion (EWSR1 pattern of FISH) in round cell sarcomas with EWSR1–non-ETS fusions." (PMID 39839837, 2024).
ganglioglioma (3 papers, 2024 to 2025). A well differentiated, slow growing neuroepithelial neoplasm composed of neoplastic, mature ganglion cells and neoplastic glial cells. "The EWSR1::PATZ1 fusion was already known in soft‐tissue sarcomas and was first discovered in a CNS tumor (specifically, in a ganglioglioma) in 2016." (PMID 39583630, 2024). "Since its initial identification in a CNS tumor in 2016, the EWSR1::PATZ1 fusion has been reported across diverse primary CNS tumors, including NEpT, ependymoma, ganglioglioma, pleomorphic xanthoastrocytoma, low-grade glial/glioneuronal tumors, astroblastoma and glioblastoma." (PMID 40575153, 2025).
hemangioma (3 papers, 2021 to 2025). A benign vascular lesion characterized by the formation of capillary-sized or cavernous vascular channels. "Also, recently reported novel markers for EWSR1-NFATC2-rearranged round cell sarcoma such as NKX2-2 and NKX3-15,6,11 were negative in the vascular malformations/hemangiomas with EWSR1-NFATC2 rearrangement and SBCs." (PMID 34081036, 2021).
malignant mesothelioma (3 papers, 2020 to 2024). A malignant neoplasm of the pleura or peritoneum, arising from mesothelial cells. "Interestingly, malignant mesotheliomas were recently found to be associated with recurrent EWSR1/FUS fusions." (PMID 32664515, 2020). "Pediatric malignant mesothelioma, which is usually peritoneal and pericardial, is also known to harbor EWSR1::ATF1 rearrangements." (PMID 39769457, 2024). "Since these rearrangements are not frequently seen in malignant mesothelioma with adult onset, which is believed to be tightly correlated with asbestos or radiation exposure, the EWSR1::ATF1-positive pediatric cases are believed to present a distinct subtype of malignant mesotheliomas." (PMID 39769457, 2024). "We found a female predominance, except for cases harboring NR4A3 and SUFU malignant mesothelioma, and most patients were around 60 years at diagnosis, but those harboring ALK or EWSR1/FUS::ATF1 gene fusions were younger." (PMID 39059063, 2024).
pancreatic neuroendocrine tumor (3 papers, 2020 to 2024). Pancreatic endocrine tumor, also known as pancreatic neuroendocrine tumor (PNET), describes a group of endocrine tumors originating in the pancreas that are usually indolent and benign, but may have the potential to be malignant. "Other reported cancers with EWSR1::BEND2 include rare pancreatic neuroendocrine tumors, one case of a pancreas islet cell tumor, salivary carcinomas, and one case of an atypical carcinoid tumor of the lung." (PMID 38339014, 2024). "In pancreatic NETs, EWSR1::BEND2-fusions have only been once reported." (PMID 36690805, 2023).
round cell liposarcoma (3 papers, 2010 to 2024). A poorly differentiated liposarcoma, characterized by the presence of solid sheets of primitive round mesenchymal cells and the absence of myxoid stroma. "On the other hand, the DDIT3 gene is known to be rearranged in myxoid/round cell liposarcomas, which can fuse with either EWSR1 or FUS, and these fusions serve as diagnostic markers for this entity." (PMID 38275873, 2024). "EWSR1 gene rearrangement is characteristic of EFT, but is also present in extraskeletal myxoid chondrosarcoma, desmoplastic small round cell tumor, and a subset of myxoid/round cell liposarcomas." (PMID 20598147, 2010).
salivary gland tumors (3 papers, 2013 to 2025). "In previous reports, the positive rate of the EWSR1 fusion gene in HCCC was 82-92%, serving as a point of differentiation from other salivary gland tumors with pallid cells." (PMID 40291188, 2025). "Fortunately, more than 80% of HCCC tumors harbor this unique EWSR1::ATF1 fusion and EWSR1 rearrangement, which distinguishes HCCC from other salivary gland tumors." (PMID 38429827, 2024).
sinonasal carcinoma (3 papers, 2022 to 2025). "Single nucleotide polymorphism (SNP) array and EWSR1 gene fluorescence in situ hybridization (FISH) analyses were conducted on SMARCB1-deficient sinonasal carcinomas." (PMID 40366517, 2025). "EWSR1 gene FISH analysis was successfully conducted on all SMARCB1-deficient sinonasal carcinomas." (PMID 40366517, 2025). "The majority of SMARCB1-deficient sinonasal carcinomas demonstrate homozygous deletion of the SMARCB1 gene and frequently harbor gene loss flanking the SMARCB1 gene, including the EWSR1 gene." (PMID 40366517, 2025). "These two cases, wherein FISH detected no EWSR1 and SMARCB1 gene abnormalities, might represent a different tumor type from SMARCB1-deficient sinonasal carcinoma." (PMID 38836164, 2024). "However, Case 2 was positive for p63, p40, and CK5/6 and harbored the EWSR1 translocation, characteristics which renal cell-like sinonasal carcinoma does not express." (PMID 35094698, 2022).
soft (3 papers, 2010 to 2025). "The EWSR1::NFATC2 fusion (case 10) showed an encapsulated soft tissue neoplasm composed of clusters of epithelioid tumor cells forming acinar-like structures, within abundant myxoid stroma." (PMID 39636306, 2025). "EWSR1 gene rearrangement is identified in only 50% of the soft tissue myoepithlelial carcinoma." (PMID 28390395, 2017).
spindle cell sarcoma (3 papers, 2022 to 2026). A malignant mesenchymal neoplasm composed of spindle-shaped cells. "Round cell sarcomas with EWSR1–non-ETS fusions are round, and spindle cell sarcomas with EWSR1 or FUS fusions involving partners irrelevant to the ETS gene family." (PMID 36983010, 2023).
vascular neoplasm (3 papers, 2017 to 2025). A benign, intermediate, or malignant neoplasm arising from vascular tissue including arteries, veins, venous sinuses, lymphatic vessels, arterioles and capillaries. "We present a case of a woman with a “difficult‐to‐diagnose” multifocal cutaneous vascular neoplasm showing an EWSR1::NFATC2 translocation." (PMID 40037835, 2025). "Here, we present a challenging case of a multifocal cutaneous vascular neoplasm, which ultimately revealed an EWSR1::NFATC2 translocation." (PMID 40037835, 2025). "One vascular malformation patient (case 1) presented with multiple skeletal lesions, 2 of which were histologically analyzed, diagnosed as a benign vascular tumor, and confirmed to carry the EWSR1-NFATC2 fusion." (PMID 34081036, 2021). "These analyses identified an EWSR1::NFATC2 translocation, and based on these findings, the lesion was classified as a vascular neoplasm with an NFATC‐related fusion." (PMID 40037835, 2025). "Using fluorescence in situ hybridization, it was apparent that amplification of the fusion, as seen in EWSR1-NFATC2 round cell sarcomas, was absent, and that in the vascular tumors the fusion was present both in the lining cells as well as in the surrounding spindle cells." (PMID 34081036, 2021).
virus infection (3 papers, 2019 to 2025). "In conditions of bona fide virus infection, the depletion of AldoA and EWSR1 inhibited, while the depletion of ILF3-90 stimulated the infectious virion yield of both viruses." (PMID 36306280, 2022). "We identified here a particularly prominent defect in germinal center B cell infection in the absence of pre-miR-7, which was rescued by expression of anti-EWSR1 shRNAs, demonstrating the biological significance of EWSR1 repression in this cell type during virus infection." (PMID 31363027, 2019). "Thus, to maximize shRNA efficacy in the context of virus infection, we inserted anti-EWSR1 or scrambled shRNAs in place of both TMER5-derived miRNA stem-loops." (PMID 31363027, 2019).
anaplastic ganglioglioma (2 papers, 2022 to 2024). A WHO grade III neuroepithelial neoplasm composed of neoplastic, mature ganglion cells and anaplastic glial cells. "The anaplastic ganglioglioma in this cohort (Case 5) showed EWSR1-PLAGL1." (PMID 36290809, 2022).
embryonal tumors (2 papers, 2018 to 2024). "These two patients at diagnosis were classified as CNS embryonal tumors with EWSR1-PLAGL1 rearrangements based on histologic appearance and molecular data." (PMID 38639853, 2024). "Two pediatric patients with CNS embryonal tumors with EWSR1-PLAGL1 rearrangements treated at Arkansas Children’s Hospital with histopathologic and molecular data are described." (PMID 38639853, 2024). "CNS embryonal tumors with EWSR1-PLAGL1 rearrangements acquire or include a population of cells with SMARCB1 alterations that are the component that predominate at relapse, suggesting treatment aimed at this disease component at diagnosis should be considered." (PMID 38639853, 2024). "This case series presents the clinical, pathologic, and molecular data for two young patients who at presentation were diagnosed with CNS embryonal tumors with EWSR1-PLAGL1 rearrangement." (PMID 38639853, 2024).
ependymoma (2 papers, 2021 to 2024). A WHO grade II, slow growing tumor of children and young adults, usually located intraventricularly. "Whether EWSR1-PLAGL1 rearranged cases represent a novel molecular type of ependymoma or a distinctive neuroepithelial entity with histologic overlap warrants further evaluation to clarify this relationship, particularly for clinical therapeutic implications." (PMID 39228008, 2024). "However, in a very recent report, a PLAGL1:EWSR1 fusion was described in a supratentorial ependymoma of a six-year-old child." (PMID 34355256, 2021). "In EWSR1-PLAGL1 fusion cases the absence of OLIG2 and SOX10 staining with relatively solid growth pattern are ependymal-like features, though ependymoma type EMA staining was only convincingly present in one case with focal/rare paranuclear dot-like staining in two cases." (PMID 39228008, 2024).
gastric cancer (2 papers, 2022 to 2024). A primary or metastatic malignant neoplasm involving the stomach. "A total of 5 proteins, including KRT2, KRT9, DCD, EWSR1, and CACNA1G, were downregulated in gastric cancer patients in both cohorts." (PMID 38191439, 2024). "In our study, EWSR1 was shown to be differentially expressed in stages II and III of gastric cancer." (PMID 35686089, 2022).
gastrointestinal stromal tumor (2 papers, 2021 to 2022). "Some examples include EWSR1 gene rearrangement in Ewing sarcoma, MDM2 gene amplification in well-differentiated and dedifferentiated liposarcoma, and c-KIT gene mutations in gastrointestinal stromal tumor (GIST)." (PMID 33802620, 2021).
glioneuronal tumor (2 papers, 2021 to 2023). "The tumor harbored an EWSR1::PATZ1 fusion, a rare alteration that appears to define a new type of glioneuronal tumor." (PMID 37221626, 2023). "Gene fusions of PLAGL1 with EWSR1 have been reported exceptionally rarely in neoplasms of the CNS, including single cases of a SMARCB1-deficient atypical teratoid/rhabdoid tumor (AT/RT) and a glioneuronal tumor, not elsewhere classified (NEC)." (PMID 34355256, 2021).
Hepatic fibrosis (2 papers, 2018 to 2026). The presence of excessive fibrous connective tissue in the liver. "By positioning EWSR1 as a novel molecular node in fibrogenesis, this article underscores its promise as a next-generation therapeutic target for halting or reversing liver fibrosis." (PMID 41799701, 2026).
hepatocellular carcinoma (2 papers, 2021 to 2024). A malignant tumor that arises from hepatocytes. "In hepatocellular carcinoma (HCC), EWSR1 was identified as upregulated." (PMID 39769457, 2024).
inflammatory myofibroblastic tumor (2 papers, 2020 to 2023). A multinodular intermediate fibroblastic neoplasm that arises from soft tissue or viscera, in children and young adults. "Since 2/3 of AFH and epithelioid EWSR1::CREB-rearranged malignant neoplasms may express ALK protein, an epithelioid inflammatory myofibroblastic tumor (IMT) is a major differential diagnosis." (PMID 37097347, 2023).
insular carcinoma (2 papers, 2021). "Through WGS analysis, we recently identified two potentially disease-causing variants in CHEK2 and EWS RNA Binding Protein 1 (EWSR1) in a FNMTC family with patients showing PTC, micro-PTC, and insular carcinoma." (PMID 33946592, 2021). "In this study, we prioritized three potentially deleterious coding variants in three genes, namely CHEK2, TIAM1, and EWSR1 in an NMTC family with aggregation of PTC, micro-PTC, and insular carcinoma." (PMID 33692755, 2021).
major depressive disorder (2 papers, 2022 to 2024). An episode of depression lasting two or more weeks without an intervening episode of mania. "In major depressive disorder, the MANF/EWSR1/ANXA6 pathway has been suggested as a potential link between hypolipidemia and major depression." (PMID 39722850, 2024). "Meanwhile, both EWSR1 and ANXA6 were found to be significantly increased in MDD patients, and significantly correlated to depression severity (positively) and TC level (negatively)." (PMID 36585419, 2022). "Third, we only detected MANF/EWSR1/ANXA6 pathway in serum, future studies should directly detect the levels of these molecules in the central nervous system, such as cerebrospinal fluid, to further pinpoint the role of this pathway in depression." (PMID 36585419, 2022). "Moreover, based on the IPA database analysis, we hypothesized that MANF/EWSR1/ANXA6 pathway might act as a bridge between low serum lipids and depression." (PMID 36585419, 2022).
malignant rhabdoid tumors (2 papers, 2021). "In addition, FISH for an EWSR1 break-apart can be misleading in malignant rhabdoid tumors (MRTs) in which commonly the genetic region encompassing SMARCB1 is deleted that may involve the EWSR1 gene, which is located close to SMARCB1 on chr22." (PMID 33919988, 2021).
multiple myeloma (2 papers, 2021 to 2022). "EWSR1 overexpression was reported to be a poor prognostic predictor in multiple myeloma, however, to date, no investigations on the role of EWSR1 in HCC were available." (PMID 34612781, 2021).